IFNG (interferon gamma)
Diseases named in the same sentence as IFNG in open-access papers (continued):
Sharing a sentence is not in itself a finding about the gene and the disease.
dengue (continued). "For example, interferon gamma (IFN-γ), interleukin 12 (IL-12) and interleukin 18 (IL-18) are essential for an effective host immune response against dengue virus infection." (PMID 28644404, 2017). "Serum IFNγ levels were significantly higher (p = 0.007) in patients with primary dengue (mean 361.6, SD ± 399.6) when compared to those with secondary dengue infection (mean 161, SD ± 246.3)." (PMID 23883139, 2013). "Serum IFNγ levels were also significantly higher (p = 0.04) in patients with severe dengue (mean 268.8, SD ± 346.2, median 128.4, range 29.8 to 1405 pg/ml) when compared to non severe dengue (mean 174, SD ± 265.6, median 72.2, range 8.1 to 1466 pg/ml)." (PMID 23883139, 2013). "High levels of cytokines, such as TNF alpha (TNFa), IFN gamma (IFNg), have been detected in patients with severe dengue." (PMID 23978258, 2013). "In our study, we have found that immunocompetent C57BL/6 mice infected intraperitoneally with DENV-1 presented some signs of dengue disease such as thrombocytopenia, spleen hemorrhage, liver damage, and increase in production of IFNγ and TNFα cytokines." (PMID 22666132, 2012). "In summary, we have found that C57BL/6 mice infected intraperitoneally with DENV-1 presented some signs of dengue disease such as thrombocytopenia, hemorrhage, liver damage, and increase production of IFNγ and TNFα cytokines." (PMID 22666132, 2012). "Whole blood samples from 55 Thai schoolchildren aged 13-14 years were assayed for in vitro interferon-gamma (IFN-γ) induction in response to inactivated dengue serotype 2 antigen (Den2)." (PMID 20854672, 2010). "It is interesting to note that IFNγ, IL-6 and IL-8 levels were found to be higher in secondary than primary infections in a recent study of dengue-infected patients in Western India." (PMID 21206915, 2010). "In cell cultures in vitro and murine models in vivo, IFNα and IFNβ suppress early stages of dengue viral replication; whereas the type II interferon, IFNγ (produced mainly by activated T and NK cells), limits dengue viral replication at later stages." (PMID 21206915, 2010). "Cytokines that are undetectable in the blood of healthy individuals are elevated in dengue-infected patients, such as IL-1β, IL-2, IL-6, IL-8, IL-10, IL-13, IL-18, IFNγ, TNFα, and MCP1." (PMID 21206915, 2010). "First, the profile showed characteristics of a general antiviral response with up-regulation of IFNG, which is an established major antiviral cytokine in dengue disease, together with up-regulation of IL12A, a potent stimulator of IFN-γ production." (PMID 18398488, 2008). "IFNγ has been shown to increase in severe dengue (DHF/DSS) infection." (PMID 34447698, 2021). "Our initial aim was to determine if the frequency of IFNγ NS3 specific memory T cell responses were different in those with mild/sub clinical dengue infection when compared to those who were hospitalized due to dengue." (PMID 25875020, 2015). "We found that serum IL-10 and IFNγ were significantly elevated in patients with severe dengue." (PMID 23883139, 2013). "Some have shown that MIF, IL-10, IL-6, MIP-1ß and IFNγ could be used as potential predictors of severe dengue." (PMID 23883139, 2013). "In addition to increases in cytokine levels cellular markers for T-cell activation, CD69, CD38, and CCR7 have been shown to be increased in dengue infection and IFNγ secretion by dengue specific T-cells has been shown to upregulate the number of Fcγ receptors." (PMID 19941667, 2009). "Indeed, an earlier phase 1 clinical trial had showed the vaccine to be well tolerated and capable of generating adequate IFNγ T-cell responses, but poor anti-dengue neutralizing antibody responses, raising concerns about incomplete protection and breakthrough infections." (PMID 40981337, 2025).
dengue (continued). "In addition, we also found that although the magnitude and the frequency of DENV-NS3 specific T cell responses were not different in those with hospitalized and mild/sub clinical dengue infection, T cells of those with past mild/sub clinical dengue were more likely to produce IFNγ." (PMID 25875020, 2015). "Key cytokines such as interferon-gamma (IFN-γ), tumor necrosis factor (TNF)-α, and interleukin (IL)-10 are pivotal in the pathogenesis of dengue." (PMID 38910682, 2024). "Both cell populations, high and low IFNγ producers, can be valuable markers for SARS-CoV-2, dengue, and the common Zika infection in dengue-endemic areas." (PMID 39519178, 2024). "Another dengue live attenuated tetravalent vaccine (DLAV) was developed very recently and it showed a rapid increase of IFNg+TNF-α+-producing CD4+ T cells and then CD8+ T cells within 8–14 days after vaccination." (PMID 35215836, 2022). "Ex vivo and cultured IFNγ ELISpot assays for dengue virus (DENV) NS3 protein and non dengue viral proteins were carried out in 26 patients with acute DI (16 with dengue haemorrhagic fever) and 12 healthy dengue seropositive individuals from Sri Lanka." (PMID 24040431, 2013). "In vitro studies, IFNγ, IL-6, TNFα, and RANTES upregulation also have been posited as important events in dengue pathogenesis." (PMID 19941667, 2009). "Widespread endothelial dysfunction is a central pathological mechanism in dengue-related complications due to the overproduction of inflammatory mediators, such as tumor necrosis factor-alpha (TNF-α), interleukin-6 (IL-6), and interferon-gamma (IFN-γ)." (PMID 40357076, 2025). "We found that individuals who were hospitalized due to dengue did not have a significantly higher (p = 1.0) frequency of NS3-specific IFNγ ELISpot responses when compared to those with mild/sub clinical dengue infection." (PMID 25875020, 2015). "Several studies have shown that serum IL-10, IFNγ and MIF are elevated in patients in severe dengue (SD) and could be used as potential biomarkers." (PMID 23883139, 2013). "In summary, we found that patients with severe dengue had lower T cell numbers but that DV-NS3 specific T cells produced high levels of IFNγ but not IL-3, IL-13, IL-2, IL-10 or IL-17." (PMID 23209731, 2012). "This shows that irrespective of serotypes, IFNγ plays a significant role in dengue pathology." (PMID 34447698, 2021). "Using a shared immune profiling approach in two countries, we have documented previously-defined elements of anti-dengue immunity such as elevated levels of activation markers (e.g., CD57 on T cells) and increased production of inflammatory mediators (e.g., IFNβ, perforin, IFNγ)." (PMID 32150565, 2020). "However, we found that while DENV-NS3 specific T cells of those with past mild/sub clinical dengue infection were more likely to produce only granzyme B, those who were hospitalized due to dengue were more likely to have DENV-NS3-specific T cells that produce TNFα and IFNγ or TNFα alone." (PMID 25875020, 2015). "In order to determine if IL-10 could be suppressing DENV-specific T cell responses, we carried out ex vivo IFNγ ELISpots for NS3 and FEC in 10 of the patients with acute dengue and 4 healthy controls following blockade with anti-IL-10 and anti IL-10R antibodies." (PMID 24040431, 2013). "IL-10 blockade significantly increased IFNγ production, and other antiviral responses such as CD107a expression and TNFα production in response to DENV-NS3 peptides but not to non dengue viral proteins in acute dengue infection." (PMID 24040431, 2013). "We found that whilst patients with severe dengue had lower total T cell numbers, the DV-NS3 specific T cells persisted and produced high levels of IFNγ but not TNFα, IL-3, IL-13, IL-2, IL-10 or IL-17." (PMID 23209731, 2012).
Insulin resistance (145 papers, 2010 to 2026). Increased resistance towards insulin, that is, diminished effectiveness of insulin in reducing blood glucose levels. "IFNγ is also a key cytokine secreted by iNKT cells in various biological settings and has been associated with insulin resistance in cultured adipocytes and in vivo." (PMID 39484712, 2024). "Here, we show that male mice with loss of IFNγ signaling in myeloid cells (Lyz-IFNγR2−/−) are protected from diet-induced insulin resistance despite fatty liver." (PMID 38951527, 2024). "Accordingly, mice lacking Nfil3, which is critical for NK cell differentiation, or genetic loss of NCR1 or IFNγ resulted in improved insulin sensitivity, while treating mice with IL-15 to expand NK cells led to insulin resistance." (PMID 34837070, 2022). "While systemic loss of T-bet protected against the development of insulin resistance, the ablation of IFNγ, the major TH1 cytokine, only modestly improved insulin sensitivity in obese mice." (PMID 34837070, 2022). "The denominator taxa of Bacteroides identified by balance tree analysis, which were more abundant in GDM women in both T1 and T2, have been associated with serum proinflammatory interferon gamma levels, insulin resistance, and plasma glucose levels." (PMID 32209715, 2020). "IFNγ-producing NK cells in AT are associated with hyperglycaemia and insulin resistance in obese women, while a deficiency of NK cells or IFN-γ was shown to prevent the accumulation of pro-inflammatory macrophages in VAT and greatly ameliorate insulin sensitivity." (PMID 38334487, 2024). "Moreover, insulin resistance can be caused by the downregulation of insulin receptors in skeletal muscle via virally induced interferon gamma (IFN-γ)." (PMID 36947108, 2023). "IFNG produced by adipose tissue inhibits adipose tissue homeostasis, leading to insulin resistance (IR) and metabolic syndrome, and reducing IFNG levels can improve IR and metabolic syndrome." (PMID 40083347, 2025). "Supporting the observation of insulin resistance in KO mice, we found higher expression of inflammatory cytokines, including TNFα, IFNγ, IL-1β, IL-6 and IL-22, in the muscles of KO mice fed with normal diet, compared to the control mice." (PMID 41234234, 2025). "Cytokines produced by these cells, such as TNF, IFNγ and IL-1β, reach the bloodstream and contribute to the development of systemic insulin resistance (IR)." (PMID 39107476, 2024). "Following strong infection, the synergistic action of IFNγ and IL-1β on pancreatic β cells leads to an increase in insulin production that exceeds the levels required to compensate for skeletal insulin resistance." (PMID 39107476, 2024). "While the interferon-gamma overactivation or dysregulation is known to play a role in the development or exacerbation of dysglycemia by for instance promoting insulin resistance and contribute to dysglycemia." (PMID 39896818, 2024). "Insulin resistance results in reduced glucose uptake by impairing insulin signaling, which is consistent with our results; that is, LPS, TNFα, and IFNγ (LTI) treatment markedly suppresses glucose uptake and Akt activation." (PMID 36771210, 2023). "This, in turn, triggers IFNγ production by NK cells and facilitates the differentiation of inflammatory macrophages that promote insulin resistance." (PMID 34837070, 2022). "In humans, acute respiratory viral infection enhances interferon gamma (IFNγ) generation and promotes muscular insulin resistance, leading to compensatory hyperinsulinemia to preserve euglycemia and promote antiviral CD8+ T cell responses." (PMID 35711466, 2022). "IFNγ+ NK cells are positively correlated with inflammation in adipose tissue, plasma glucose levels, and insulin resistance." (PMID 35574038, 2022). "Third, SARS-CoV-2 induces the secretion of interferon-gamma and increases muscular insulin resistance and circulating insulin levels, which eventually increases the response of cluster of differentiation 8 cytotoxic T-cell (CD8 + T-cell)." (PMID 34441802, 2021).
Insulin resistance (continued). "Viral-induced interferon-gamma secretion has been demonstrated to increase muscular insulin resistance and circulating insulin levels, which, in turn, increases the cluster of differentiation 8 cytotoxic T-cell (CD8 + T-cell) responses." (PMID 34441802, 2021). "This activated proliferation of NK cells and increased production of IFNγ, which further supported the infiltration and activation of macrophages in this tissue, key to maintain the systemic inflammatory status and insulin resistance characteristic of NASH." (PMID 33679803, 2021). "Adipose tissue-resident NK cells also contribute to obesity-induced insulin resistance in adipocytes via IFNγ production leading to macrophage polarization." (PMID 33679803, 2021). "These cells can stimulate adipocytes and release pro-inflammatory factors, such as IFNγ, TNFα, IL-1β, and IL-6, leading to the development of local and systemic inflammation, insulin resistance, and type 2 diabetes." (PMID 30323806, 2018). "The link between this disturbance and insulin resistance was demonstrated by another study where IFNγ was shown to induce insulin resistance in mature human adipocytes." (PMID 30138332, 2018). "It has also been postulated that there is a relationship between insulin resistance, interferon-gamma, and inflammation." (PMID 27401171, 2016). "IFNγ, which induces adipose inflammation and insulin resistance and some other molecules were predicted to be upstream regulators that are inhibited or activated by quercetin in the EAT of mice fed the Western diet." (PMID 26499876, 2016). "Active caspase-1 can eventually process IL-1β and IL-18 precursors, serving as enhancer of multiple proinflammatory pathways including NF-κB, mitogen-activated protein kinase (MAPK), IFNγ, chemokines, and ROS and also promoting insulin resistance." (PMID 24744784, 2014). "Further, NLRP3 upregulates the pool of proinflammatory cytokines such as IL-1β, IL-18, and IFNγ and promotes insulin resistance in M1 macrophages." (PMID 24744784, 2014). "IFNγ has an increasingly apparent role in regulating not only adipocyte cytokine secretion including TNFα but also insulin resistance and infiltration of T cells into obese adipose tissue." (PMID 22276186, 2012). "The peripheral NKT cells number is also decreased in patients with NAFLD and an elevated Th1-cytokine profile dominated by the production of IFNγ is correlated with insulin resistance and NASH in obese children." (PMID 21042596, 2010). "Interestingly, B lymphocytes are emerging players in promoting inflammation associated with insulin resistance and T2D by producing IgG antibodies, which in turn enhance local TNF-α and interferon-gamma (IFN-γ) production from macrophages and T cells." (PMID 40225857, 2025). "However, under obese conditions, IFNγ-polarized M1 macrophages produce large amounts of pro-inflammatory cytokines in adipose tissues, consequently promoting insulin resistance." (PMID 39519233, 2024). "This can trigger the secretion of pro-inflammatory cytokines such as TNF-α, interleukin (IL)-6, interleukin (IL)-1, interferon gamma (IFNγ), and monocyte chemoattractant protein-1 (MCP-1) by visceral fat through the portal vein, which can then cause insulin resistance." (PMID 37508403, 2023). "Studies have shown that HP infection induces the release of pro-inflammatory cytokines such as tumor necrosis factor alpha, interferon gamma, interleukin (IL)-1, IL-6, IL-8, IL-10, IL-12, and C reactive protein and was shown to be involved in the pathogenesis of insulin resistance." (PMID 36699110, 2023). "Thereby, some key pathways could be identified which mediated these effects, e.g., the JAK/STAT pathway in IFNγ mediated insulin resistance." (PMID 35986215, 2022). "Moreover, IFNγ seems to favor insulin resistance independently of body weight changes since improved insulin resistance and diminished adipose tissue inflammation were noticed in IFNγ deficient mice." (PMID 34207683, 2021).
Insulin resistance (continued). "In addition, cytokines such as IFNγ promote insulin resistance (IR) in many tissues, including the muscle, thus reducing its glucose uptake and anabolic activity." (PMID 34835051, 2021). "The reduction in the expression of apoE and other proteins in this network may also contribute to the pro-atherogenic role of IFNγ, especially in the setting of insulin resistance." (PMID 31231209, 2019). "Thus, quercetin suppresses the accumulation and activation of immune cells and the subsequent inflammation and systemic insulin resistance, probably by suppressing the expression of leptin, TNFα, and possibly IFNγ." (PMID 26499876, 2016). "While this insulin resistance may serve as an adaptive mechanism to prioritize glucose availability for immune cells, prolonged IFNγ-driven metabolic alterations can impair glucose regulation and contribute to metabolic dysregulation in conditions such as diabetes and chronic inflammation." (PMID 40453076, 2025). "IFNγ induced metabolic pathways, such as nitric oxide (NO) production and tryptophan catabolism, which can interfere with mitochondrial function, insulin sensitivity, and lipid metabolism, exacerbating conditions like insulin resistance, obesity-related inflammation, and autoimmunity." (PMID 40453076, 2025). "This could be explained by a finding that obese patients with MASLD have increased IFNα and decreased IFNγ levels, and IFNα but not IFNγ levels are associated with the accumulation of intramuscular fat, an important contributor to insulin resistance." (PMID 40076848, 2025). "Furthermore, in spontaneously insulin-resistant rats, an increase in the levels of several inflammatory cytokines was observed, such as IL-2, IL-6, IL-1β, IL-4, IL-5, IL-12p70, stimulating factor granulocyte and macrophage colonies (GM-CSF), interferon gamma (IFNγ) and TNF-α." (PMID 35053356, 2022). "Different models of insulin resistance induction have been applied to SGBS cells including chronic high insulin and/or glucose or pro-inflammatory factors such as interferon gamma, TNFα, or IL-29." (PMID 35986215, 2022). "When treated with IFNγ, IFN-β, or TNF, 3T3-L1 cells showed increased insulin resistance through reduction of PPARγ levels." (PMID 34835051, 2021). "A consequence of up-regulation of IFNγ production is an elevation of neopterin, the concentration of which correlates with abdominal obesity, HDL cholesterol, and insulin resistance." (PMID 30862026, 2019). "Adipose tissue macrophages are important contributors to insulin resistance and STAT4 was shown to be required for M1 macrophage polarization and IFNγ production in response to IL12/18." (PMID 28400678, 2017). "We have demonstrated that Themis KO mice exhibit an accelerated onset of insulin resistance when fed HFD, despite the lack of quantitative differences regarding infiltration of pathogenic IFNγ-producing CD8+ T cells in VAT compared with its WT counterpart." (PMID 41282140, 2025). "Furthermore, a significant action in interfering with insulin signaling and insulin-stimulated glucose uptake is pursued by interferon-gamma (IFN-γ), eventually leading to insulin resistance and DM." (PMID 37239990, 2023). "Additionally, the tumor secretes interferon-gamma (IFN-γ), which mediates the development of insulin resistance via reduced glucose and fatty acid [FA] uptake, leading to enhanced lipolysis in WAT." (PMID 36465353, 2022). "ApoE and 8 other members of this macrophage protein network were dysregulated in the presence of insulin resistance via a mechanism dependent on IFNγ and independent of changes in their transcript levels." (PMID 31231209, 2019). "The mechanism may involve TLR4 activation in macrophages as it was shown that TLR4 requires STAT4 for IFNγ production in response to IL12 and ablation of TLR4 in the myeloid compartment prevents insulin resistance in obese mice." (PMID 28400678, 2017).